IL1B (interleukin 1 beta)
Diseases named in the same sentence as IL1B in open-access papers (continued):
Sharing a sentence is not in itself a finding about the gene and the disease.
colitis (continued). "N. brasiliensis‐derived EVs were used as treatment in a mouse model of chemical‐induced colitis and demonstrated to reduce IL‐6, IL‐1β, IFNγ and IL‐17a and increase IL‐10 expression." (PMID 39113589, 2024). "They observed that mucosal IL-1β levels (as a potent pro-inflammatory marker) and histological colitis scores were significantly lower in calcium-fed mice." (PMID 38500985, 2024). "Pro-inflammatory cytokines such as IL-17, IL-1β, IL-6, and TNF-α have been identified as the key driver in colitis-associated inflammation." (PMID 39744127, 2024). "Based on that, we measured if DCA-induced reduction in the expression level of NLRP3 would reduce the level of cleaved caspase-1 and hence IL-1β level in oxazolone-induced colitis as measured by Western Blot." (PMID 37902927, 2024). "This study revealed that L. gasseri ATCC33323 can ameliorate physiological damage in mice with colitis, reduce the extent of colitis, decrease inflammatory cell infiltration, and decrease the levels of the inflammatory factors IL-1β, IL-6, and TNFα." (PMID 39250508, 2024). "During the inflammatory response caused by colitis-induced model or IBD, IL-1β along with other proinflammatory cytokines such as TNF-α and IL-6 orchestrate the inflammatory response within the lamina propria." (PMID 38323035, 2024). "IL-1β levels were reduced by 40% in colitis mice treated with the probiotic mixture compared to untreated mice, but this was not significantly different." (PMID 39201260, 2024). "Intestinal bacteria can induce IL-1β release and promote colitis via recruited monocytes, which are the primary source of IL-1β." (PMID 39221251, 2024). "We further measured the production of pro-inflammatory cytokines, TNF-α, IFN-γ, IL-6, IL-1β, and IL-17 in colonic tissue of colitis mice." (PMID 39085655, 2024). "Consistently, higher levels of pro‐inflammatory Il1b, Il6, Tnf, Cxcl2 and Cxcl10 mRNA were detected in the colon of Otub2–/– mice, further consolidating the more severe colitis in these mice." (PMID 39358938, 2024). "Concentrations of the cytokines IL-23, IL-17, IL-6, TNF,and IL-1β were higher in the colon from the colitis group comparedto the control groups, confirming the presence of colitis." (PMID 39022369, 2024). "They found that exogenous IL-1β reduced colonic Th2 cytokine expression and ameliorated colitis, suggesting that decreased IL-1β levels altered the immune status and exacerbated colitis." (PMID 39519191, 2024). "Se supplementation can decrease the expression levels of main inflammatory cytokines TNF-α, IL-1β, and IL-6 in inflammatory diseases, such as rheumatoid arthritis, atherosclerosis, and colitis." (PMID 38321393, 2024). "In this study, both the HWB and LWB treatments demonstrated a significant reduction in pro-inflammatory factors (TNF-α, IL-6, and IL-1β) in the colon tissues of colitis mice." (PMID 38254526, 2024). "After injection of MSC-Evs, the expression of NF-κB p65 in colon macrophages can be downregulated, and the production of NO, IL-1β, and IL-18 can be reduced, thus alleviating the symptoms of colitis." (PMID 39185411, 2024). "Assessment of the mRNA expression of the prototype Th17 gene Il17 and the innate immune response gene Il1b demonstrated a marked increase with DSS colitis in the WT mice that was significantly attenuated in Cth–/– mice." (PMID 39427081, 2024). "L. casei LC2W improved symptoms of colitis induced with E. coli O157:H7 by protecting tight junctions and reducing IL-1β, TNF-α and IL-6 in the colon." (PMID 36986118, 2023). "The expressions of RFZ1, IL-6, TNF-α, and IL-1β were also increased in CD68+ macrophage detected by IF staining in the colon from mice with colitis." (PMID 37733446, 2023). "Comprehensive bioinformatics analysis and in vivo validation using the mouse model of colitis identified IL1B, CXCL1, MMP1 and MMP10 as markers of UC." (PMID 38169708, 2023).
colitis (continued). "Mice with LF-Colitis and LF-CAC showed a significant increase in plasma IL-1β, IFNγ, and IL-12 levels compared to the LF-Ctr mice, which were reduced in the HF-Colitis and HF-CAC groups compared to their LF group counterparts." (PMID 36768196, 2023). "The acute inflammatory response in DSS-induced colitis is represented by increased expression of IL-1β, IL-6, and TNF-α in the colon." (PMID 36768278, 2023). "Experimental evidence showed that SYK inhibitor significantly alleviated DSS-induced and TNBS-induced colitis by regulating TGFβ, TNFα, and IL-1β, which are also important in the course of PSC." (PMID 37229242, 2023). "In our study, we observed that DSS-induced colitis was characterized by excessive inflammatory indicators, such as the upregulation of proinflammatory cytokines (IL-17, IL-6, IL-1β) in the colon and prevailing Th17/Treg cells in the MLNs." (PMID 37143672, 2023). "In a rat model, inhibition of the NLRP3 inflammasome by INF39, an acrylate derivative and irreversible inhibitor of NLRP3, decreased IL-1β secretion and alleviated colitis induced by 2,4-dinitrobenzenesulfinic acid in rats." (PMID 36669831, 2023). "IL-1β serves as the vital pro-inflammatory cytokine that mainly stems from activated macrophages and promotes the development of colitis by increasing the intestinal permeability." (PMID 37762155, 2023). "The inflammatory cytokines including TNF-α, IL-1β, IL-6, and IL-10 were higher in colitis mice than those in control mice (P < 0.01)." (PMID 36768559, 2023). "A gut microbiota analysis revealed a marked elevation of B. intestinalis in patients with ICB toxicity, along with an overexpression of mucosal IL-1β in patient samples of colitis and mice." (PMID 37834058, 2023). "Preclinical studies supported the effectiveness of anti-IL-1β monoclonal antibodies 7F IgG and FL-BsAb1/17 in mitigating colitis, while anakinra showed efficacy in the UC model of primary anti-TNF non-responders." (PMID 38274809, 2023). "In our previous study, we found that QCS ameliorated DSS-induced colitis by inhibiting the expression of Caspase-1 and IL-1β during inflammasome activation." (PMID 36762118, 2023). "All treatment groups significantly reduced the proinflammatory cytokines “TNF-α and IL-1β” compared to the DSS-induced colitis group." (PMID 37545572, 2023). "These components play a role in the NLRP3 inflammasome activation, which drives intestinal inflammation in colitis by consequent production of IL-1β and IL-18." (PMID 37513865, 2023). "Colon acetic acid challenge in the colitis control significantly (p < .0001) elevated serum IL‐1β levels (4.9 ± 0.07 ng/L) compared to 1.9 ± 0.07 ng/L of the noncolitis group." (PMID 37249276, 2023). "Oral administration of the β-naphthoflavone (an AhR agonist) decreased the severity of colitis and the production of pro-inflammatory cytokines, such as TNF-α, IL-6, and IL-1β in DSS-induced colitis." (PMID 36672703, 2023). "Our study showed a central role of IL-1β in regulating neutrophil functions and the colonic inflammatory status in C.difficile-driven inflammations in colitis." (PMID 36951545, 2023). "In this study, high concentrations of colonic TNF-α, IL-6, and IL-1β were observed in mice with colitis, which was in agreement with a previous study." (PMID 37762155, 2023). "We found that the relative mRNA expression of Rfx1 and M1 macrophage–related genes Il6, Tnf, and Il1b were significantly increased in the colon tissue of mice with colitis compared with the control group." (PMID 37733446, 2023). "In colitis mice, IL-10 potently suppresses the pro-IL-1β production transcriptionally in macrophages and its maturation to IL-1β, and alters Th17 cytokine dependency required for colitis pathogenesis." (PMID 37834058, 2023).
colitis (continued). "We also found that Olfm4 deletion leads to an enhanced immune response and inflammation in the progression of colitis, characterized by enhanced expression of complement Il-1β, Il-6, and Mcp-1 and activation of the NF-κB pathway." (PMID 37151883, 2023). "Studies have shown that elevated IL-1β correlates with the severity of acute inflammation and that inhibition of IL-1β expression alleviates the symptoms of colitis." (PMID 37492574, 2023). "In the DSS colitis model of colitis, Ufbp1fl/fl/VillinCre mice show increased pro‐inflammatory cytokine (IL‐6, IL‐1β) production and are sensitive to tissue damage." (PMID 36680403, 2023). "This activation leads to the maturation and secretion of IL-1β, further exacerbating the progression of colitis." (PMID 37367886, 2023). "As previously reported, the mRNA levels of inflammatory cytokines, Il6 (the gene encoding interleukin 6 (IL-6), Il17a, Tnf (the gene encoding tumor necrosis factor α), and Il1b, were increased in the colon of Vdr(+/−) mice with DSS-induced colitis." (PMID 36834927, 2023). "It has been studied that the occurrence of colitis is related to the production of IL‐1β by macrophages and IL‐1β maturation is dependent on caspase‐1 activation." (PMID 36840499, 2023). "Dexamethasone (p < .01, F.C: −9.09) and QA at 30 (p < .05, F.C: −2.2), 60 (p < .01, F.C: −4.3), and 100 (p < .001, F.C: −12.98) mg/kg attenuated the IL‐1β expression in comparison to the colitis values." (PMID 37647443, 2023). "It is proved that oral TDNPs can reduce proinflammatory cytokines (TNF-α, IL-6 and IL-1β), upregulate antioxidant gene HO-1 to relieve colitis in mice and accelerate colitis regression." (PMID 37033644, 2023). "PA/CCMTS-P showed excellent anti-inflammatory effects both in vitro and in vivo, which obviously reduced the secretion of TNF-α, IL-6, IL-1β, and IL-18 after LPS stimulation in Raw264.7 cells, and the expression of IL-1β and IL-18 at the colitis site in vivo." (PMID 36843930, 2023). "Inhibition of colitis was defined by decreased expression of the pro-inflammatory cytokines IL-1β and TNF-α in M1 macrophages." (PMID 36768556, 2023). "β2-integrins (ITGB2) are required for IL-1β dependent induction of IL-22 by ILC3s, ITGB2 deficiency is associated with impaired IL-22 responses in colitis." (PMID 37016023, 2023). "The activation of LXRs in a mouse colitis model can suppress the expression of inflammatory factors such as IL-1β, IL-6, IL-17A, TNFα, and chemokines such as CXCL1/KC, CXCL2/MIP2, CXCL8/IL-8, CCL2/MCP1 and CXCL10 in the colon tissue." (PMID 37720208, 2023). "NLRP3 is the most studied NLR and has been proven to be mediated in DSS-induced colitis by regulating IL-1β secretion." (PMID 37371485, 2023). "While IL-1β blockade reduced ICI colitis severity in mice, IL-6 inhibition improved tumor response to ICI and suppressed irAE symptoms in preclinical models, and is being pursued as an approach to alleviate irAEs in patients." (PMID 36622383, 2023). "Apart from the involvement of neutrophils, there are other shared characteristics of DSS and ICI-related colitis, such as the elevation of IL-1β or IL-6." (PMID 37511839, 2023). "The expression of proinflammatory genes, such as IL‐6, TNF‐α and IL‐1β was significantly lower in the colon of KO mice than in WT mice in both acute colitis and tumour samples." (PMID 37341064, 2023). "In the present study, PHI efficaciously suppressed the expressions of TNF-α, IL-1β, and IL-6 in colitis mice." (PMID 36768559, 2023). "In previous studies, ursolic acid has been proved to relive DSS-induced colitis in mice by reducing the content of malondialdehyde, IL-1β and TNF-α and increasing superoxide dismutase activity in mice colon tissues." (PMID 37161415, 2023). "In DSS-induced colitis, DL can reduce the ulcerative colitis-related colorectal inflammation, including significant reduce in IL-1β." (PMID 37540386, 2023).
colitis (continued). "The mLN cells in DSS colitis showed increased mRNA and protein levels of IL-1β, IL-6, IL-12, and IL-23, which were considerably increased by additional treatment with FimH." (PMID 38077339, 2023). "Studies have reported that TRAF2 plays a negative regulatory role in the expression of TLR-stimulated proinflammatory cytokines and inhibits the occurrence of colitis by reducing the expression of LPS-, poly(I:C)- and IL-1β-induced proinflammatory cytokines." (PMID 38037100, 2023). "Taken together, our findings suggested that elevated IL-1β expression driven by C. difficile in colitis contributed to neutrophil infiltration and intestinal inflammatory responses." (PMID 36951545, 2023). "Accordingly, we found that integrin β6 deficiency remarkably decreased the release of pro-inflammatory cytokines including TNF-α, IL-6 and IL-1β in the intestinal tissues of colitis." (PMID 37223685, 2023). "NR4A1 inhabits pyroptosis by transcriptionally inhibiting NLRP3 and IL-1β and colocalizing with NLRP3 in trans-Golgi to alleviate pathogenic bacteria-induced colitis." (PMID 37238692, 2023). "Turmeric-derived exosome-like nanoparticles suppressed the expression of pro-inflammatory cytokines, such as TNF-α, IL-6, and IL-1β, promoted the levels of antioxidant genes, particularly HO-1 by inactivating NF-κB pathway, and alleviated colitis." (PMID 37653406, 2023). "Experimental studies showed that FC alleviated DSS-induced colitis symptoms, reduced inflammatory cytokines release, and suppressed the expression levels of IL1β, COX2, MMP3, IL-17 and RORγt in colon tissues." (PMID 37161415, 2023). "Because luminal NO is elevated in colitis, this study instead focused on tumor immunoreactivity of IL-1β (a known inducer of iNOS) and iNOS." (PMID 38187473, 2023). "Nevertheless, the precise mechanism regarding how IL-1β is involved in C. difficile-induced inflammation in colitis requires further investigation." (PMID 36951545, 2023). "The robust neutrophil infiltration was probably regulated by increased interleukin (IL)-1β levels because hindering the production of IL-1β by the inhibitor MCC950 significantly alleviated colitis induced by C. difficile in DSS mice." (PMID 36951545, 2023). "Inflammatory cytokines including IL-1β, TNF-α, and IL-6 are linked with effects of the fecal microbiome on ICI colitis; IL-6 also drives irAEs in other organs." (PMID 36622383, 2023). "To characterize the anti-inflammatory therapeutic potential of PR1P in TNBS-induced colitis, we quantified plasma levels of the pro-inflammatory mediators IL-1β, IL-6 and TNF-α on Day 7 following necropsy." (PMID 37187742, 2023). "The elevation in the levels of IL-1β and IL-23 in colon tissues indicates the severity and extent of colitis." (PMID 35566122, 2022). "Supportive of this finding, macrophages of Nod2 knockout murine models with colitis showed increased production of IL-1β." (PMID 36203564, 2022). "Our data showed that knockout or blockade of GPR84 significantly reduced IL-1β level in both colitis mice and M1 macrophages, suggesting the possible involvement of NLRP3 inflammasome." (PMID 34912006, 2022). "Colitis in Cdcs1+/+Il10ra−/− mice is characterized by marked elevation of inflammatory cytokines, including Il12b, Infg, Il1b and Tnf17." (PMID 35013585, 2022). "During colitis in mice, expression of IL-22 was negatively impacted by accumulating Tregs which suppressed the release of IL-23 and IL-1b from macrophages." (PMID 36189323, 2022). "NF-κB mediated the production of various proinflammatory cytokines, such as IL-6, TNFα, and IL-1β, which regulated inflammatory responses in colitis induced by DSS (M. L. Chen and Sundrud 2016; Neurath 2014; Fantini and Pallone 2008)." (PMID 35433693, 2022). "Pro-inflammatory cytokines, including Il-6, IFN-α, and IL-1β, are the main characteristics of colitis." (PMID 36139747, 2022).
colitis (continued). "The IL-38 deficiency that aggravated DSS colitis was associated with elevated gene expression and protein levels of NLRP3 inflammasome and enhanced IL-1β signaling at the time of sacrifice." (PMID 35693797, 2022). "Recent studies suggest that high levels of pro-inflammatory cytokines, including IFNγ, TNFα, IL1β, IL6, and MCP1, are implicated in DSS-induced colitis." (PMID 35888062, 2022). "A recent study in patients with melanoma treated with combined immune checkpoint blockade (CICB) targeting CTLA-4 and PD-1 who developed ≥ grade 3 colitis demonstrates an intestinal overexpression of IL1β and TNF compared to normal tissue." (PMID 35432346, 2022). "Previous research reported that an antimurine IL-1ß antibody decreased IL-6 mRNA expression and alleviated pathological symptoms of DSS-induced colitis, suggesting that IL-1β targets itself and IL-6 for progressing colonic inflammation." (PMID 35672695, 2022). "Our consequences displayed that anethole considerably decreased the level of MDA, increased the TAC, and decreased the gene expression of inflammatory cytokines including TLR4, TNF-α and IL-1β in the colon tissue of the colitis group." (PMID 35432569, 2022). "Il-1β and Il-6, proinflammatory cytokines upregulated in the hippocampus of our mice with acute colitis, are potent suppressors of neurogenesis." (PMID 36232813, 2022). "We measured the levels of inflammatory cytokines such as IL-1β, TNF-α, IL-6, and IL-10, which are linked to colitis." (PMID 36456585, 2022). "The IL-1β concentration was significantly higher in colitis mice compared to normal control mice (18.21 ± 3.01 pg/mL vs. 8.65 ± 1.54 pg/mL, p < 0.05)." (PMID 35741032, 2022). "In this context, the serum levels of IL-4, IL-1b, and TNFαwere examined, and we found that these increased cytokines in colitis mice were suppressed by CYN and mesalamine, as evidenced by ELISA experiments." (PMID 36278202, 2022). "The important role of inflammasomes in controlling homeostasis of the intestinal tract has been further demonstrated by amelioration of experimental colitis through blockade of the inflammasome effector molecules IL-1β and IL-18 in different murine models." (PMID 36524121, 2022). "Previous reports on blockade of NLRP3 with this specific NLRP3 inhibitor effectively limited the induction of DSS colitis in mice, and inhibits NF-κB, IL-1β, caspase-1 and MPO activity." (PMID 35693797, 2022). "Of note, Btk KO mice develop severe TNBS-induced colitis, which can be improved by IL-1β blockade indicating a central role of inflammasome activation in BTK-dependent colitis development." (PMID 36524121, 2022). "We demonstrated that SBLF ameliorated DSS-induced colitis in mice by reducing colonic IL-1β expression and inflammation." (PMID 36552376, 2022). "The acute inflammatory response that occurs in mice with DDS-induced colitis is at least partially related to the overexpression of the inflammatory cytokines IL-1β, IL-6, and TNF-α." (PMID 36431883, 2022). "Selective deletion of IL-1β or neutralization of TNF-α in Ly6Chi monocytes suppresses colitis in mice." (PMID 34912006, 2022). "Our in vivo studies showed that apigenin inhibited TNF-α, IL-6, and IL-1β secretions in colitis of DSS-induced mice." (PMID 36590200, 2022). "Biopsies of inflamed colon mucosa from patients with IBD exhibited increased LTA and IL1B expression, including a subset of patients with active colitis on anti-TNF therapy." (PMID 35077396, 2022). "In support, glucosamine was able to reduce colitis-associated symptoms in DSS-treated mice by reducing TNF-α, IL-1β, and NF-kB expression in the colonic mucosa, and increasing the expression of ZO-1 and occludin tight junction proteins." (PMID 36009057, 2022). "Our findings have led us to propose a paradigm wherein stressor exposure during periods of mild colitis leads to an inhibition of colonic cytokines and inflammatory factors (such as IL-1β and iNOS) that have protective responses to intestinal bacteria." (PMID 35216112, 2022).